CCM2L (CCM2 like scaffold protein)
Synonyms: C20orf160; dJ310O13.5
Tractability: PROTAC: ubiquitination databases record sites on it.
Gene: Protein-coding gene on chromosome 20 (32,010,408 to 32,032,185, forward strand). Ensembl gene ENSG00000101331.
Subcellular location (Human Protein Atlas): Nucleoplasm
Gene Ontology:
Molecular function: protein binding
Biological process: heart morphogenesis; endothelium development; vasculogenesis
Genetic constraint (gnomAD): Loss-of-function variants: 32 observed, 47.37 expected, observed/expected ratio (o/e) 0.68, 90% interval 0.51 to 0.91. The upper end of that interval is the gene's LOEUF score, 0.91, which puts it in group 3 of 6, group 1 being the genes least tolerant of losing a copy. Missense variants: 633 observed, 655.72 expected, observed/expected ratio (o/e) 0.97, 90% interval 0.9 to 1.03. Synonymous variants: 318 observed, 286.11 expected, observed/expected ratio (o/e) 1.11, 90% interval 1.01 to 1.22.
Homologues: Orthologues: macaque CCM2L (98% identical), pig CCM2L (96% identical), dog CCM2L (95% identical), rabbit CCM2L (91% identical), mouse Ccm2l (89% identical), rat Ccm2l (89% identical), tropical clawed frog ccm2l (65% identical), chimpanzee CCM2L (65% identical), zebrafish ccm2l (40% identical). Paralogues in human: CCM2 (34% identical).
Diseases named in the same sentence as CCM2L in open-access papers:
CCM2L is named in the same sentence as 2 diseases in open-access papers, as found by Europe PMC text mining. Sharing a sentence is not in itself a finding about the gene and the disease. The quoted sentences say what the papers report.
cardiomyopathy (1 paper, 2021). A disease of the heart muscle or myocardium proper. "However, the abnormal down-expressions of heg1, ccm2, and ccm2l in TFD-induced cardiomyopathy could be restored by NXT treatment confirmed by qRT-PCR validation." (PMID 34775978, 2021).
vascular disorder (1 paper, 2025). A general term used to describe any disease affecting blood vessels]. "Our findings support future studies to further investigate whether CCM2L variants influence GVM severity or contribute to the spectrum of GLMN-related vascular disorders." (PMID 40894452, 2025).